INS (insulin)
Diseases named in the same sentence as INS in open-access papers (continued):
Sharing a sentence is not in itself a finding about the gene and the disease.
Insulin resistance (continued). "Because cancer patients exhibit insulin resistance, the expression of Akt protein, a key component of insulin signaling, was examined." (PMID 30555329, 2018). "Insulin dysregulation in horses is a metabolic condition defined by high insulin concentrations in the blood and peripheral insulin resistance." (PMID 29716602, 2018). "These high GH concentrations lead to anti-insulin effects in both liver and adipose tissues, which increase insulin resistance." (PMID 30374329, 2018). "We studied 405 men and 528 women from the European Group for the study of Insulin Resistance - Relationship between Insulin Sensitivity and Cardiovascular disease cohort." (PMID 29855339, 2018). "Hyperglycemia develops when there is insufficient insulin secretion to compensate for insulin resistance." (PMID 30041479, 2018). "In agreement with this, insulin-resistant mice on a high fat diet were treated with PAHSAs and showed improvement in both insulin resistance and glucose tolerance." (PMID 30361530, 2018). "Type 2 diabetes mellitus is characterized by impaired insulin secretion, insulin resistance, overproduction of glucose by the liver, and an abnormal fat metabolism." (PMID 30097599, 2018). "Plasma insulin levels were significantly higher in KKAy than KK, and significantly lower in KKAy + Dapa than KKAy, indicating improvement in insulin resistance." (PMID 29891844, 2018). "In the current study we observed that epicatechin supplementation resulted in improved fasting insulin and insulin resistance." (PMID 29672527, 2018). "Decreased glycogen synthesis due to impaired insulin-stimulated glucose transport plays a key role in developing muscle insulin resistance." (PMID 30199540, 2018). "Among these people, more than 90% suffered from type 2 diabetes (T2D) which is characterized by hyperglycemia, insulin resistance, and insufficient insulin secretion." (PMID 30687391, 2018). "In the early stages of disease, pancreatic β-cells retain the ability to secrete insulin but the patient develops insulin resistance, resulting in the compensatory secretion of more insulin from pancreatic β-cells to maintain normal blood glucose levels." (PMID 30524480, 2018). "Insulin resistance is defined as the disability of insulin to regulate glucose and lipid metabolism in peripheral tissues even at elevated insulin levels in the blood." (PMID 29570673, 2018). "Insulin resistance is reflected by the rates of reduced glucose uptake (GU) into the key insulin-sensitive tissues, skeletal muscle, liver and adipose tissue." (PMID 29535167, 2018). "Compound K enhanced insulin secretion via the upregulation of GLUT2 in MIN6 pancreatic β-cells, and improved insulin levels and insulin resistance to combat T2DM." (PMID 29765322, 2018). "In vivo, WSZYF decreased fasting blood glucose (FBG), insulin concentration, insulin resistance index, triglyceride (TG), total cholesterol (TC), and free fatty acids (FFA) in T2DM rats." (PMID 30356368, 2018). "The rapid onset of insulin resistance upon treatment with MitoPQ argues for an acute signaling mechanism between mitochondria and insulin signaling/GLUT4 trafficking and that mitochondrial oxidants are a distal component in the ontogeny of insulin resistance." (PMID 29599292, 2018). "Women with PCOS also feature a decreased beta cell compensation in insulin resistance, as well as a decreased insulin sensitivity, alongside an increase of PERI." (PMID 30158974, 2018). "NAFLD patients showed higher levels of insulin and homeostatic model assessment of insulin resistance (HOMA-IR) (P < 0.001 for both) compared to controls." (PMID 30076407, 2018). "Most of the studies using high dose GH supplementation were associated with at least a short term (<6 months) increase in serum insulin and insulin resistance." (PMID 29724029, 2018). "The elevated plasma insulin throughout the SAL clamp in the HFD group compared to the LFD group further confirms obesity‐induced insulin resistance." (PMID 30047243, 2018).
Insulin resistance (continued). "The inability of insulin to regulate glucose was assumed to be because of insulin resistance, but insulin resistance was measured as the inability of insulin to regulate glucose." (PMID 30307959, 2018). "The dominant hallmarks of T2D are progressive pancreatic β cell degeneration and insulin resistance coupled with higher insulin secretion from pancreatic β cell and lower insulin degradation." (PMID 29751685, 2018). "A higher level of palmitoleic acid has beneficial effect on insulin sensitivity in case of metabolic diseases, and its administration in animal models being effective for reducing insulin resistance and hepatic lipid accumulation." (PMID 30216387, 2018). "Surprisingly, we firstly found that artemether not only increased insulin sensitivity and improved insulin resistance, but also reduced food intake and body weight increase rate, which makes up for the shortcomings of this type of insulin sensitizer." (PMID 29862294, 2018). "Hepatocyte-specific deletion of Snail1 enhances insulin-stimulated lipogenesis in hepatocytes, exacerbates dietary NAFLD in mice, and attenuates NAFLD-associated insulin resistance." (PMID 30013137, 2018). "It has been reported that TNF-α induced insulin resistance in skeletal muscles is attributed to the induction of IRS-1 phosphorylation on serine residue followed by the deterioration of insulin signaling." (PMID 29872751, 2018). "In regards to metabolism, co-treatment with rosiglitazone, a PPARγ ligand and insulin sensitizer, has been shown to partially rescue glucose intolerance and insulin resistance in rapamycin-treated rats." (PMID 29579736, 2018). "A recent study indicated that S1P counteracts the insulin pathway and contributes to hepatic insulin resistance in vitro as well as in vivo." (PMID 29510489, 2018). "Treatment of PSTi8 significantly decreased these index of insulin resistance associated with PST and enhance glucose clearance, insulin sensitivity and suppress gluconeogenesis." (PMID 29880906, 2018). "Insulin resistance was subsequently triggered because of the abnormally increased serum insulin level of the diabetic model group." (PMID 30337946, 2018). "Recent studies on insulin signaling in the heart in animal models of insulin resistance have reported varying and potentially divergent results, possibly reflecting the different models and experimental conditions." (PMID 30089498, 2018). "Insulin resistance (IR) is characterized by decreased sensitivity of insulin target tissues (adipose, muscles, and hepatocytes) to normal concentrations of insulin, resulting in reduced ability of the body to control glucose." (PMID 30135600, 2018). "Chronic glucocorticoid exposure also induces selective insulin resistance that impedes the inhibitory effect of insulin on hepatic glucose output." (PMID 29915558, 2018). "In rodents, chronic exposure to a high fat/high sugar diet induces peripheral insulin resistance and changes brain insulin signalling." (PMID 29813096, 2018). "The relationship between adipose tissue and insulin resistance is well-known: the verdict being that with increased adipose mass, and thus weight gain, there is an impairment of insulin action, leading to insulin resistance." (PMID 29601521, 2018). "Insulin resistance is a pathological condition in which cells fail to respond to the normal signal of insulin to store glucose in the tissues." (PMID 30134566, 2018). "Central insulin signaling dysregulation precedes the onset of peripheral insulin resistance in two mice models of AD, Tg2576 and 3xTg-AD." (PMID 29743868, 2018). "Since insulin resistance is characterized by a reduced number of receptors and the downregulation of insulin signaling, IR expression and Akt activation levels were measured and compared in the brains of different groups." (PMID 30134549, 2018). "Cardiac insulin signaling can be impaired due to the altered fatty acid metabolism to induce insulin resistance." (PMID 30344301, 2018).
Insulin resistance (continued). "By genome-wide association meta-analysis, 17 genetic loci associated with fasting serum insulin (FSI), a marker of systemic insulin resistance, have been identified." (PMID 29487953, 2018). "Namely, in obese subjects with prediabetes, decreased Glu-OC blood levels were noticed, which was inversely associated with homeostatic model assessment for insulin resistance (HOMA-IR index) and insulin." (PMID 30388806, 2018). "The increase of free fatty acids in plasma (+119%) of HFD-fed rats led to insulin resistance as fasting glucose and insulin levels as well as the HOMA-IR index were significantly higher (+70%, 12 times and 15 times, respectively)." (PMID 30271528, 2018). "Low birth weight associates with adult insulin resistance, hypertension, coronary-artery disease and type 2 diabetes mellitus (T2DM), possibly due to maternal malnutrition or an insulin-resistant/-deficient genotype of the foetus." (PMID 30514227, 2018). "New research highlights the importance of high levels of circulating insulin as both a driver of weight gain and insulin resistance." (PMID 30271382, 2018). "Skeletal muscle and adipose tissue were clearly insulin resistant in subjects with whole body insulin resistance, while insulin-stimulated liver GU was only slightly lower compared to the insulin-sensitive group." (PMID 29535167, 2018). "Metrnl increases insulin induced AKT phosphorylation, hence, it has been found that Metrnl deficiency leads to adipocyte insulin resistance." (PMID 30212581, 2018). "GDM is the result of increased insulin production which cannot compensate for the increased insulin resistance." (PMID 29854818, 2018). "We studied osteogenic differentiation, osteocalcin gene expression, and osteblast-mediated insulin secretion, using cultured MG-63 human osteoblast-like cells that underwent glucotoxicity and insulin resistance." (PMID 28866834, 2018). "Ang II seems to interact with insulin metabolism, as the 3C group showed higher insulin resistance than the 2C group." (PMID 30088535, 2018). "Plasma levels of hepcidin, IL-6, Serum Insulin and ferritin using ELISA method, serum iron levels using a spectrophotometric method, and Insulin resistance by using HOMA were measured in the two groups of PCOS (case group) and healthy subjects (control group)." (PMID 31239849, 2018). "We determined the serum insulin and glucagon levels by ELISA kits and calculated insulin resistance index (HOME-IR)." (PMID 29862294, 2018). "In those studies, EF was assessed by measuring blood flow, and insulin action was assessed by using various methods (including hyperinsulinemic euglycemic clamp, minimal modeling, and homeostasis model of insulin resistance)." (PMID 29593654, 2018). "Insulin resistance is defined as a reduced ability of tissues or cells to respond to normal levels of insulin, resulting in obesity and type 2 diabetes." (PMID 30583568, 2018). "As mentioned in the previous topics that insulin plays an important role in brain function, several studies demonstrated that neuronal insulin resistance can be found under obese condition." (PMID 30233495, 2018). "The unique aspect of our results is the higher levels of plasma LPS in HIV patients treated with HAART and the strong positive correlation between plasma LPS and measurements of insulin resistance such as fasting insulin, HOMA and the TG/HDL-C ratio." (PMID 29434676, 2018). "While there is evidence that GDM can occur in all three settings, the vast majority (~80%) of GDM cases present as β-cell dysfunction on a background of chronic insulin resistance, to which the normal insulin resistance of pregnancy is partially additive." (PMID 30373146, 2018). "Taken together, these data suggest that SRA promotes adipocyte differentiation and insulin sensitivity through up-regulating insulin signaling and simultaneously inhibiting signaling downstream of TNFα, which otherwise would promote insulin resistance." (PMID 30238005, 2018).
Insulin resistance (continued). "Insulin resistance refers to a pathological condition in which the body cannot respond normally to insulin." (PMID 29765322, 2018). "We next investigated the effects of MitoPQ on other insulin-regulated processes, as insulin resistance has been reported to be somewhat selective." (PMID 29599292, 2018). "The relationship between obesity and T2D is well documented and has been attributed to progressive decline in insulin secretion leading to concomitant rise in insulin resistance." (PMID 29449808, 2018). "The phosphorylation of IRS-1 on serine residues is associated with insulin resistance induced by cytokines such as TNF-α, since it inhibits IRS-1 tyrosine phosphorylation leading to impaired insulin signaling." (PMID 29463262, 2018). "Insulin resistance is a pathological condition in which the insulin receptor (IR) is insensitive to insulin and signaling pathway cannot be sufficiently activated." (PMID 29513799, 2018). "Experimental studies in humans have demonstrated that increased sedentary behavior is associated with reduced energy expenditure, the development of an insulin-resistance state, impaired insulin sensitivity, and an accumulation of abdominal fat." (PMID 29686951, 2018). "Blockade of CB1R in the liver alleviates diet-induced insulin resistance by increasing insulin sensitivity." (PMID 29497784, 2018). "Several of these IRS kinases (e.g., S6K1, PKC) are both inducers of insulin resistance and activated in response to insulin." (PMID 30563117, 2018). "Hyperglycaemia (high blood sugar levels) results when the β-cells fail to compensate insulin resistance with excess insulin output." (PMID 29304014, 2018). "At the end of the 6-week intervention, there was a significant improvement in the insulin-to-glucose ratio, indicating lessened insulin resistance." (PMID 30072950, 2018). "Chronic hyperinsulinemia accompanies insulin resistance in the liver, adipose tissue, and skeletal muscle, which are the primary targets of insulin." (PMID 29718998, 2018). "Together, these data suggest that the hepatic insulin/Snail1 axis ameliorates insulin resistance in obesity, presumably through decreasing liver steatosis." (PMID 30013137, 2018). "Acute treatment of rapamycin enhances insulin secretion and prevents nutrient-induced insulin resistance." (PMID 30011848, 2018). "This is also supported by another cross-sectional analysis that observed significant positive relationships between egg consumption and fasting glucose, insulin or insulin resistance, although the difference was very small." (PMID 29098427, 2018). "The failure of insulin-stimulated translocation of GLUT4 to the plasma membrane is an early step in the development of insulin resistance." (PMID 30089498, 2018). "In the treatment model, compounds 5 and 6 also significantly attenuated the body weight gain, and the rise in fasting plasma glucose and insulin levels in the mice with pre-existing insulin resistance and obesity induced by 12-week HF feeding." (PMID 30223438, 2018). "Higher insulin levels and insulin resistance can reduce renal excretion of urate, and contribute to increase uric acid synthesis." (PMID 29425155, 2018). "Fasting plasma glucose (FPG) and fasting plasma insulin were used for the calculation of homeostasis model assessment-estimated insulin resistance (HOMA-IR)." (PMID 30675157, 2018). "IRS1 and IRS2 are required for downstream signaling through additional serine/threonine kinases and their phosphorylation by JNK results in decreased insulin signaling and insulin resistance." (PMID 30200608, 2018). "In our SF rats, the decreased amount of γ-glutamylcysteine level is associated with impaired γ-GCS expression that can be attributed to insulin resistance because insulin has been described to enhance γ-GCS transcription or activity in hepatocytes." (PMID 29675131, 2018).
Insulin resistance (continued). "Insulin resistance is the key pathophysiological feature of obesity and T2DM, and is caused by imbalances in insulin action in peripheral tissues, insulin secretion, or both." (PMID 29747466, 2018). "Decreased Akt phosphorylation at the insulin-responsive active site (Ser473 and Thr308) following insulin stimulation have been well documented in insulin resistance." (PMID 29433422, 2018). "Insulin resistance is defined as an organ failure to respond to insulin and consequently increases circulating blood glucose." (PMID 30603087, 2018). "In contrast, chemerin impaired insulin signaling and blocked insulin-stimulated glucose uptake by human skeletal muscle cells and induced insulin resistance in rat cardiomyocytes." (PMID 29279348, 2018). "Homeostasis Model Assessment of Insulin Resistance (HOMA-IR: HOMA−IR=fasting insulin(μU/mL)×fasting glucose(mmol/l)/22.5) has been used to estimate the level of IR in the existing studies." (PMID 30463387, 2018). "Uncontrolled FA release from WAT promotes lipotoxicity, which is characterized by inflammation and insulin resistance that can lead and worsen type 2 diabetes and can further impair brain insulin signaling, starting a vicious cycle." (PMID 32232085, 2018). "As a result of insulin resistance, the body needs higher levels of insulin to help glucose enter cells." (PMID 29799467, 2018). "Most commonly, insulin resistance is used to refer to the inability of insulin to stimulate glucose disposal." (PMID 30151057, 2018). "Insulin resistance is a physical condition, which is demarcated as a state that needs additional insulin to produce biological effects with decreasing glucose uptake in muscle and adipose tissue." (PMID 30564116, 2018). "AUCins/glu denotes the levels of insulin secretion and DI represents the ability of islet β-cells to compensate against insulin resistance." (PMID 29568712, 2018). "Insulin resistance, i.e. decreased biological response to insulin, and low-grade systemic and adipose tissue (AT) inflammation play a role in the development of metabolic complications associated with the excess of body fat." (PMID 29737494, 2018). "If one considers endothelial insulin resistance as an early event in the development of the MS, it will remain to be resolved how ingestion of a western diet can impair endothelial insulin action." (PMID 29209827, 2018). "Insulin resistance is first accompanied by pancreatic β-cell adaptation, with increased β-cell mass and insulin secretion (hyperinsulinemia) to prevent a rise in blood glucose." (PMID 30249977, 2018). "Olanzapine challenge induced remarkably increased body weight, fasting insulin, homeostasis model assessment-insulin resistance index, and TCF7L2 protein expression in liver, skeletal muscle, and adipose tissues." (PMID 29713286, 2018). "In the present work, we further confirmed that DHEA-induced PCOS mice exhibited whole-body insulin resistance by fasting serum insulin measurement and HOMA-IR evaluation." (PMID 29552281, 2018). "Meanwhile, as indicators of pancreatic function and insulin resistance, fasting insulin and HOMA-IR were significantly improved after ginger consumption." (PMID 29541142, 2018). "Late pregnancy is characterised by peripheral insulin resistance with a compensatory increase in insulin secretion and β-cell mass." (PMID 29593656, 2018). "Resistin is a novel adipokine identified that suppresses glucose tolerance and insulin sensitivity, and has been proposed to be an important link between obesity, insulin resistance and type 2 diabetes (T2D)." (PMID 30524378, 2018). "Elevated circulating FFA promote ectopic lipid deposition in peripheral tissues, decrease glucose uptake and oxidation, increase insulin resistance, and lead to lipotoxicity induced impairment of insulin secretion from β-cells." (PMID 29661693, 2018).